CD4 (CD4 molecule)
Diseases named in the same sentence as CD4 in open-access papers (continued):
Sharing a sentence is not in itself a finding about the gene and the disease.
anemia (continued). "After 1–2 months of ARV’s, severe anaemia was significantly reduced in all groups, though remained highest in the low CD4 cohort." (PMID 24192332, 2013). "In our data, incident anemia was associated with female gender, lower BMI, advanced WHO stage, and lower CD4 count." (PMID 24069036, 2013). "Our finding is similar to previous literature in that BMI levels are predicted by not only CD4 counts but also by anemia and hemoglobin levels." (PMID 23573191, 2013). "A low baseline CD4+ count was weakly predictive of paradoxical MC IRIS, and mild anaemia and a history of current or past TB were associated with unmasking MC IRIS." (PMID 23152745, 2012). "Additional work is needed to elucidate this question, especially since depletion of CD4+ T cells significantly alleviates anaemia in a murine model." (PMID 22853732, 2012). "A logistic regression analysis showed age, CD4+ percentage and WHO clinical staging to be independently associated with the presence of anaemia." (PMID 23114115, 2012). "In multivariable analysis, after adjusting for baseline age, cohort, CD4+ cell count, WHO stage, log viral load, anaemia, and weight, men had a 31% higher risk of death than women (adjusted HR [AHR] 1.31, 95% CI 1.22–1.41)." (PMID 22973181, 2012). "Anaemia was associated with previous clinical AIDS disease or other infection, CD4 count, HIV viral load, female sex, age, and low body mass index." (PMID 22289654, 2012). "Anaemia was independently associated with young age (p <0.0001), advanced HIV WHO disease stage (p = 0.034) and low CD4 percentage (p = 0.048)." (PMID 23114115, 2012). "Other baseline factors associated with mortality were age >35 y, CD4+ cell count, WHO stage, anaemia, weight, and viral load." (PMID 22973181, 2012). "Compared with unexposed women, HAART-exposed women were older (30.3 vs. 28.9, p < 0.001), had a lower median CD4 count (154 cells/mm3 vs. 191 cells/mm3, p < 0.001), and a lower rate of anaemia (46% [416/912] vs. 57% [57/100], p = 0.03)." (PMID 21843356, 2011). "The cat was feline immunodeficiency virus positive and showed CD4+ T-cell depletion, severe leukopenia, anemia and a multicentric monoclonal B-cell lymphoma." (PMID 20167134, 2010). "Improvement of immunosuppression prior to switches to AZT-containing regimens, as evidenced by increased BMI and increased CD4 T cell counts, further decreased the risk of AZT-induced anaemia." (PMID 21047391, 2010). "As shown, more severe levels of anemia were also found to correlate with decreasing CD4 counts; in our study we correlated using hemoglobin and CD4+ cell counts, finding similar data." (PMID 20727136, 2010). "The incidence of anemia was strongly and consistently associated with the progression of HIV disease as measured by CD4 count." (PMID 19922646, 2009). "Using unresolving noncytopathic Friend virus (FV) infection in mice, we showed that unregulated CD4+ T cell response to FV caused IFN-γ-mediated bone marrow pathology and anemia." (PMID 19006695, 2008). "Collectively, these results established a mechanism for virus-specific CD4+ T cell-induced anemia in FV-infected Rag1−/− hosts and its suppression by Treg cells." (PMID 19006695, 2008). "Although both groups developed similar levels of anaemia, mice that received IL-10−/− T cells lost significantly more weight and succumbed to infection more rapidly than mice that received WT CD4+ T cells." (PMID 18401464, 2008). "Our results demonstrated that the local IFN-γ production by virus-specific CD4+ T cells in response to unresolving FV infection led to bone marrow pathology, which manifested as anemia." (PMID 19006695, 2008). "Therefore, this study not only reaffirms the connection between anemia and cytopenias with low CD4+T cell counts but also highlights the predictive value of thrombocytopenia and anemia in PLWH for INR." (PMID 40134788, 2025). "The severity of anemia has been correlated with low CD4 count." (PMID 39742334, 2024).
anemia (continued). "Patients with low CD4+ cell counts in the first episode of VL develop frequent relapses that, despite the use of appropriate medications, persist chronically, with VL symptoms such as anemia, cachexia, hepatosplenomegaly, and decreased blood cell counts." (PMID 38491526, 2024). "Traditional risk factors for anaemia like CD4+ count and tuberculosis infection were not significant." (PMID 39186572, 2024). "Through the backward elimination variable selection procedure, the final model included four variables as risk factors for discontinuing TDF due to renal adverse events ‒ higher age, presence, and severity of anemia, lower baseline eCrCl, and lower CD4 cell count." (PMID 38175824, 2024). "CSHs should closely monitor children who present with a baseline CD4 cell count below the threshold, or with a low hemoglobin level or anemia, and should place more emphasis on working with the caregivers of HIV-infected children in order to achieve good ART adherence during the follow-up period." (PMID 37205221, 2023). "The prevalence of anemia was almost twice in patients with baseline CD4+ cell count ≤200 cells/mm3 as compared to patients with CD4+ cell count >200 cells/mm3 (64.0% versus 36.4%) in which 6.8% of patients with low CD4+ cell count tend to develop severe anemia." (PMID 37234694, 2023). "Additionally, previous studies support our finding that anemia was common among patients with lower CD4+ T cell count, especially in patients with CD4+ T cell count < 200 cells/μL." (PMID 37858044, 2023). "Children with iron deficiency anemia had significantly higher levels of immature T-cells CD1 a(+) as well as lower levels of mature T-lymphocytes CD4(+) and T-lymphocytes CD8(+) when compared to the control, indicating a defect in T-cell maturation in iron deficiency anemia patients." (PMID 36986181, 2023). "Early enrolling of HIV-infected adults into ART with continuous monitoring of CD4 cell count and good management initiated before the advancement of the clinical stage might reduce the observed high prevalence of anemia." (PMID 38085717, 2023). "The effect of anemia on the death risk of PLWHA was consistent and evident, especially in males and participants with a higher BMI, CD4+ T-lymphocyte count (CD4), lower white blood cell count (WBC), total bilirubin (TBIL), normal alanine aminotransferase (ALT), and fasting plasma glucose (FPG)." (PMID 36873867, 2023). "In the current study, HIV-infected adults with a CD4 cells count below 200 cells/mm3, BMI below 18.5 kg/m2, clinical stage III or above, and having HIV infection for five or more years have increased the risk of anemia." (PMID 38085717, 2023). "In the multivariable Cox regression analysis, only CD4 cell count, anemia status, ART adherence level, ever taking TPT, and initiation of ART within 7 days of admission showed statistically significant associations with incidence of OIs among HIV-infected children receiving ART." (PMID 37205221, 2023). "However, there was significant positive correlation between CD4 count and anemia [r = 0.16, P = 0.02, 95% CI]." (PMID 35245289, 2022). "Among HIV-infected low BMI (-5.4 kj/kg/day, 95%CI: -10.4, -0.4), moderate anaemia (-13.8 kj/kg/day, 95%CI: -18.8, -8.8), CD4 counts ≤200cells/uL (-9.9 kj/kg/day, 95%CI: -16.5, -3.3) and log CRP (-9.7 kj/kg/day, 95%CI: -12.4,-7.0) were associated with lower PAEE." (PMID 35061774, 2022). "Predictors included common indicators of altered immune systems based on white blood cell (WBC) (x 109/L) and CD4+ T-cell count, anemia based on red blood cell count (RBC) (x 1012/L), age, gender, 18S copy number/μL, Pfs25 ddPCR concentration, and PfMGET ddPCR concentration." (PMID 36189366, 2022). "It is already known that in the case of HIV-positive pregnant women with anemia or low levels of CD4 lymphocytes in pregnancy, their products of conception may be affected in terms of intrauterine development." (PMID 35208597, 2022).
anemia (continued). "Anemia was lower in patients with CD4 count ≤200, 10.7% (5.4% in both groups)." (PMID 35245289, 2022). "Moderate and severe anemia prevalence gradually increased as CD4 count declined." (PMID 36474196, 2022). "The positive correlation between CD4 count and anemia might be due to leukemia in HIV patients where an increased production of lymphocytes increases production of WBC that could increase CD4 and this suppresses RBC to cause anemia." (PMID 35245289, 2022). "The greatest effect size was seen with positive LAM and anemia, but the greatest population impact could be attributed to lower CD4 count and anemia, reflecting the high prevalence of these factors among the study population." (PMID 35855000, 2022). "Here, in a post hoc analysis, we describe the association of anemia and blood Hb levels to the clinical TB score and select baseline variables including BMI, MUAC, vitD3, ESR, CD4, and CD8 T cell counts, as well as systemic levels of the T-cell-produced Th1 cytokine IFN-γ and pro-inflammatory IL-6." (PMID 36014824, 2022). "However, in OH infected, anemia in patients with the CD4 counts of ≤500 cells/μl and ≥500 cells/μl were each 50% (17/34)." (PMID 35245289, 2022). "In addition, the prevalence and severity of anemia increasing with a decrease in CD4 count was discovered." (PMID 36474196, 2022). "Factors often reported to increase risk anemia include ART regimens containing zidovudine, more advanced disease stage or low CD4+ count, nutritional status or body mass index <18.5 kg/M2, female sex, duration of HAART, presence of opportunistic infections, and low baseline hemoglobin level." (PMID 35333889, 2022). "The relationship between CD4 counts and anemia is likely because of increased viral burden as the disease progresses, which may contribute to anemia through increased cytokine-mediated bone marrow suppression." (PMID 36474196, 2022). "Moreover, children who had a CD4 count below the threshold level were increased the hazard of anemia by 1.9 times as compared to children with a CD4 count above the threshold level." (PMID 33785009, 2021). "Besides, Children who had a CD4 count below the threshold level had an increased hazard of anemia of 1.9 times that of children with a CD4 count above the threshold level [AHR: 1.9 (95% CI: 1.09, 3.37)]." (PMID 33785009, 2021). "The risk factors for mortality, in addition to high fungal burden, were slow clearance of infection, altered mental status, older age, low CD4+ T-cell count, low weight, and anemia, which have all been previously identified as predictors of mortality in HIV cohorts in general." (PMID 34869498, 2021). "Participants with anaemia had a significantly lower CD4/CD3 lymphocyte count." (PMID 34068196, 2021). "Furthermore, the average CD4 count of women with moderate/severe anaemia increased from 124.1 to 287.3." (PMID 33425126, 2020). "In the multivariate Cox analysis adjusted for BMI, CD4+ count and VL, the early mortality group showed higher rates of anaemia, with a significant difference in the severity of the disease, when compared with the group of patients who survived to one year from enrolment (p<0,001)." (PMID 33170905, 2020). "Those with CD4 T-cells < 350/uL are utmost expected to develop anemia." (PMID 33911826, 2020). "In fact, both patients had a very low CD4+ T cell count at baseline (25 cells/mL and 98 cells/mL), were hospitalized for severe anaemia (7 days after anti-TB treatment initiation) and received blood transfusion; additionally, they were both sputum smear-negative at 2 months." (PMID 32590942, 2020). "The adjusted odds of having an adverse pregnancy outcome was 2.5 (95% confidence interval, 1.0–6.5; P = .048) times higher in IPT-unexposed women compared with IPT-exposed women after controlling for maternal age, CD4 count, viral load, antiretroviral regimen, body mass index, and anemia." (PMID 31631221, 2020).
anemia (continued). "Additionally, the clinical and immunological characteristics related to nutritional program incompleteness were: baseline WHO clinical stage, functional status, ART status, duration on ART, baseline CD4 count, anaemia and nutritional status." (PMID 32339181, 2020). "Among those with HCV coinfection, CD4 < 100 was associated with a HR for incident anemia of 10.20 (95% CI 8.01, 12.98), while for those without HCV coinfection, the HR was 5.01 (95% CI 3.39, 7.42; p-value for low CD4-HCVcoinfection interaction =0.001)." (PMID 32197585, 2020). "Moreover, from our sub-group analysis, we observed that undernutrition is more common among HIV-positive adults with advanced disease stage, CD4 counts less than 200 cells/mm3, having diarrhea, having anemia and living in rural areas." (PMID 32322404, 2020). "In this study, anemia prevalence increases with decreasing CD4+ T-cell count." (PMID 30759131, 2019). "In addition, others factors related to the child's health status such as the occurrence of chronic pathologies, reported episodes of diarrhea, anemia, and low CD4 levels affecting the growth of children have also been identified in other contexts." (PMID 31318938, 2019). "The prevalence of anaemia was 16.67%, 42.50%, 55.77% and 61.14% in patients with a CD4 counts of >350, 200–350, 50–199 and <50 cells/μl, respectively, increasing with decreasing CD4 counts (P = 0.033, P = 0.001, P < 0.001)." (PMID 30816082, 2019). "In unadjusted analyses, mortality risk was higher in patients aged 55 years or older, men, ART-experienced patients, those unable to walk, patients with severe anaemia (haemoglobin < 80 g/l), patients with CD4 cell count < 100 cells/μl, and those with positive urine TB-LAM tests." (PMID 30951533, 2019). "In addition to variation its variability in magnitude, anemia is influenced by factors which are associated with adult HIV/AIDS patients on ART, socio demographic factors, ART regimen, and CD4 count." (PMID 30909968, 2019). "On the other hand, it may be important to consider that the Presto gives significant over-estimations of CD4 count and Hgb, and this may result in cases of advanced diseased or anemia being missed." (PMID 30794637, 2019). "Previous studies using Cox regression analysis identified male gender, single marital status, bedridden functional status, advanced WHO clinical stage, underweight, low CD4 count, severe anaemia, and older age as independent risk factors of mortality among PLHIV which was not seen in this study." (PMID 30805359, 2019). "Likewise, the odds of having anemia were almost 5 times higher among participants with CD4 count < 200 cells/mm3 compared with participants with CD4 count ≥ 500 cells/mm3 [(AOR: 4.8;( 95% CI 1.14,12.42)]." (PMID 30909968, 2019). "Similarly, a Chinese study reported increased prevalence of anemia with increasing age and decreasing CD4+ T-cell count; and had identified older age as one of the significantly associated factors with an increased risk of anemia." (PMID 30759131, 2019). "The baseline characteristics of the cases and controls in the CTF case-control population differed significantly by the following baseline characteristics: country (p = 0.001), BMI (p = 0.001), prior TB diagnosis (p = 0.01), CD4 T cell count, hypoalbuminemia, and anemia (p < 0.001 for all)." (PMID 30244671, 2018). "Similarly 42.5% (48/113) of patients were within the age of 30 to 40 years and 49.4% of patients with CD4 cell count < 200 cells/μl developed anemia." (PMID 29568529, 2018). "Similarly 21.2% of patients with the age of < 30 years and 16.2% of patients with CD4 cell count < 200 cells/μl developed anemia." (PMID 29568529, 2018). "Collectively, these data support the conclusion that both the medullary changes in erythropoiesis and peripheral anemia seen in experimental VL arise as a consequence of CD4+ T cell activation and IFNγ production, independently of any potential contributions from splenomegaly." (PMID 30619317, 2018).
anemia (continued). "Anemia prevalence was 88.9% for patients with CD4 count < 50 cells/μl and 85.7% for CD4 count 50-99 cells/μl, 81% for CD4 count 100-199 cells/μl, 65.3% for CD4 count 200-349 cells/μl, 32.7% for CD4 count 350-500 cells/μl and 28.6% for CD4 count > 500 cells/μl (p = 0.000)." (PMID 29632668, 2018). "In the present study, we show using an experimental murine model that CD4+ T cell-dependent adaptive immune responses to L. donovani underpin anemia through a pathway that involves repressed BM erythropoiesis consequent on alterations in the stromal microenvironment of the erythropoietic niche." (PMID 30619317, 2018). "Higher scores of the carotenoids and other nutrients factors were associated with reduced hazards of CTF in univariable models, but not in multivariable models that adjusted for sex, age, country, BMI, baseline TB status, CD4 count, viral load, treatment arm, anemia, and hypoalbuminemia." (PMID 30244671, 2018). "Deaths occurred in 86 (11.6%) patients which were independently associated with male gender (16.0% versus 9.0%, p = 0.015), being divorced (OR = 2.7, p < 0.001), WHO stages 3 and 4 (OR = 2.3, p = 0.05), CD4 <200 cells/μl (OR = 3.4, p < 0.001), and severe anemia (OR = 6.6, p < 0.001)." (PMID 28702270, 2017). "In our study that includes HIV-infected patients from an Italian cohort with mild anemia and median CD4+ cells > 400/mm3 at baseline, cART significantly increased CD4+ cell count in patients of group A (none HIV/HCV infected), but not in group B (62% of them was HIV/HCV coinfected)." (PMID 29258550, 2017). "Risk factors for HAND include the nadir CD4+ T-cell count, indicating the depth of immunosuppression achieved during the course of HIV disease, older age at seroconversion, anemia, delay in initiating ART, and the presence of HIV RNA in the CSF and plasma, as well as comorbidity." (PMID 28427421, 2017). "Residence, malaria infection and CD4 + count were identified as predictors for anemia." (PMID 28184306, 2017). "None of the CSF iron biomarkers was associated with nadir CD4+ T-cell count, hemoglobin level, or anemia (data not shown)." (PMID 28427421, 2017). "Patients with more advanced HIV disease or a lower CD4 cell count had higher rates of anemia." (PMID 28116101, 2017). "Anemia is the most common haematological abnormality in HIV seropositive patients and is predictive of HIV-associated morbidity and mortality, independently of CD4+ count." (PMID 29258550, 2017). "In our study, we investigated if factors such age, gender, educational level, alcohol consumption, travel hours from the treatment centres, sharing of results with a family member or friend,anemia,CD4 count on first diagnosis and WHO clinical staging were associated with delayed entry." (PMID 27390926, 2016). "However, the result of the adjusted analysis showed that, the age groups of 18–29 years, marital status (widowed), presence of anemia, and having CD4 counts of less than 200 cells/mm3 were significantly and independently associated with undernutrition." (PMID 27468351, 2016). "In our study, we found no significant change in the T lymphocyte numbers and CD4/CD8 ratio in cases with iron deficiency anemia compared with controls." (PMID 27893677, 2016). "It is known that HIV works by linking itself to the surface of the individual'simmunological cells, mainly destroying the CD4 cells, although it can also reach bloodcells, platelets and leukocytes, leading to a situation of fatigue, dyspnea, anemia,infections and hemorrhage." (PMID 27384466, 2016). "When grouped based on haemoglobin concentration, participants with anaemia had a significantly lower CD4/CD3 lymphocyte count (P < 0.0001 each) with corresponding lower mean values of red cell indices (HCT, P < 0.0001; MCV, P < 0.0001; MCH, P < 0.0001; MCHC, P = 0.0017)." (PMID 27092270, 2016).